MX1 (MX dynamin like GTPase 1)
Diseases named in the same sentence as MX1 in open-access papers (continued):
Sharing a sentence is not in itself a finding about the gene and the disease.
leukemia (31 papers, 2013 to 2025). A malignant (clonal) hematologic disorder, involving hematopoietic stem cells and characterized by the presence of primitive or atypical myeloid or lymphoid cells in the bone marrow and the blood. "To further clarify the role of NOX2 for the observed effects of NMH on the development of Kras-induced leukemia and survival, we generated triple transgenic mice that expressed the Mx1-Cre-inducible LSL-KrasG12D on a NOX2-deficient background (Nox2−/−)." (PMID 30323311, 2019). "Rodent Mx1 proteins accumulate in the nucleus in characteristic dots closely associated with promyelocytic leukaemia (PML) nuclear bodies." (PMID 29986463, 2018). "The in vivo expansion of leukemia was markedly reduced in triple transgenic mice where KRAS was expressed in hematopoietic cells of animals with genetic NOX2 deficiency (Nox2−/− × LSL-KrasG12D × Mx1-Cre)." (PMID 30323311, 2019). "To investigate whether the NrasG12D/G12D; Mx1‐Cre+; Golga7KO mice acquired additional oncogenic mutations during leukemia development, we performed whole exome sequencing (WES) analysis on BM cells and spleen cells from 5 independent moribund Golga7KO samples and 3 independent NC samples." (PMID 40091521, 2025). "Also, NrasG12D/G12D; Mx1‐Cre+; Golga7HET mice had prolonged OS (median, 124 days; P = 0.0061) when compared to Golga7WT counterparts, suggesting a moderate dose‐dependent inhibitory effect of Golga7 loss on NrasG12D‐driven leukemia development." (PMID 40091521, 2025). "We then hypothesized that the AMP population observed in Runx1+/R188QMx1-CreCbfb+/56M mice is functionally different from that observed in Mx1-CreCbfb+/56M mice with loss of leukemia-initiating ability, similar to that observed in Runx1fl/flMx1-CreCbfb+/56M mice." (PMID 40763310, 2025). "In order to determine whether Klf5 deficiency impairs B-cell leukemogenesis once leukemia have been initiated, we generated Mx1-Cre;Klf5flox/flox mice where the deficiency of Klf5 can be induced after transplantation in recipient mice where leukemogenesis has already been initiated." (PMID 30038712, 2018). "Similar to the leukemia developed in Mx1-CreCbfb+/56M mice, increased c-Kit+ leukemic cells were detected in peripheral blood, spleen, and bone marrow of diseased Runx1f/+Mx1-CreCbfb+/56M mice." (PMID 40763310, 2025). "The lower RUNX1 chromatin binding seems to correlate with longer latency for leukemia development in the Mx1-CreCbfb+/56M-ΔHABD mice." (PMID 40763310, 2025). "Surprisingly, transplantation of spleen cells from Mx1-CreCbfb+/56M-ΔHABD leukemic mice led to leukemia with shorter latency in the recipient mice than transplantation of spleen cells from Mx1-CreCbfb+/56M mice." (PMID 40763310, 2025). "Although PI3K deletion prolonged survival in the KMT2A-MLLT3 AML model, Pik3ca – deleted mice eventually still develop leukemia with a similar phenotype as control WT;Mx1-Cre mice." (PMID 40791365, 2025). "These mice developed leukemia with a median survival of 164 days, which is modestly prolonged in comparison with Runx+/+Mx1-CreCbfb+/56M mice." (PMID 40763310, 2025). "Expression of EWS-FLI1 in cells with the activated Mx1 promoter in E/F; Mx1-cre mice led to leukemia where the mice presented with severe hepatomegaly, splenomegaly, and anemia followed by rapid death." (PMID 26462019, 2015). "We used this profile to characterize cells from control mice and pIpC induced E/F; Mx1-cre mice with late stage leukemia." (PMID 26462019, 2015). "Since Gata1 is one of the most highly up-regulated genes in erythroblasts of E/F; Mx1-cre animals, Gata1 immunostaining was used as a reliable biomarker in the leukemia mouse model to trace erythroblasts." (PMID 26462019, 2015). "The AMP population harbors pre-leukemia-initiating cells in Mx1-CreCbfb+/56M mice." (PMID 40763310, 2025).
leukemia (continued). "Principal component analysis (PCA) revealed that LK cells from control and Mx1-CreCbfb+/mDE mice, which do not develop leukemia, clustered together, and were distinctly separated from LK cells from Mx1-CreCbfb+/56M and Mx1-CreCbfb+/56M-ΔHABD mice, which do develop leukemia." (PMID 40763310, 2025). "Since Mx1 assemblies have often been observed to be distributed in juxtaposition to promyelocytic leukemia (PML) bodies in the nucleus, we tested whether this is also the case for TMxB." (PMID 32907985, 2020). "To address the role of NOX2, which is the dominant source of enzymatically derived ROS in normal and leukemic myeloid cells, in KRAS-driven leukemia we utilized double transgenic LSL-KrasG12D × Mx1-Cre mice where hematopoiesis was biased toward the NOX2+ granulocyte/monocyte linage." (PMID 30323311, 2019). "To determine whether IL1RL1 continues to be expressed in the LSC-enriched CSF2RB− population after leukemic transformation, we stained leukemia cells isolated from Cbfb+/56M, Mx1-Cre+ mice for IL1RL1 and KIT." (PMID 30742053, 2019). "In addition, Mx1-Cre+; Cbfb+/56M; Runx1+/lz mice show significantly delayed leukemia development as compared to Mx1-Cre+; Cbfb+/56M; Runx1+/+ mice." (PMID 27542261, 2016). "In some studies aberrant expression of CXCR7, DNTT, GPR56, H1F0, and MX1 is seen in leukemia." (PMID 26517675, 2015). "The enrichment of these populations was also observed in the peripheral blood, where only 0.04% and 0.10% of the cells from peripheral blood of E/F; control mice were CD43+/CD45− and CD71+/CD117+, respectively, compared to 24.57% and 21.96% in E/F; Mx1-cre mice with leukemia." (PMID 26462019, 2015). "Furthermore, SMMHC binding enrichment at TSSs was lower in Mx1-CreCbfb+/56M-ΔHABD cells compared with Mx1-CreCbfb+/56M cells, which may have contributed to delayed leukemia development in Mx1-CreCbfb+/56M-ΔHABD mice." (PMID 40763310, 2025). "Additionally, the upregulated DEGs in Mx1-CreCbfb+/56M cells also positively correlated with CHYLA_CBFA2T3_TARGETS_UP and negatively correlated with CHYLA_CBFA2T3_TARGETS_DN, suggesting a critical role for CBFA2T3 during leukemia initiation in Mx1-CreCbfb+/56M mice." (PMID 40763310, 2025). "Furthermore, YK-4-279 treatment extended the survival of E/F; Mx1-cre mice with leukemia." (PMID 26462019, 2015). "To further validate the relationship between O-GlcNAcylation and m6A, we isolated bone marrow cKit+ cells from OGTfl/fl and Mx1-Cre; OGTfl/fl mice and transduced them with the MLL-AF9 virus to induce leukemia." (PMID 39849461, 2025). "Following induction of Mx1-Cre recombinase by repeated pIpC injections at 4 weeks of age, FLT3ITD/ITD; Llgl1+/+ animals developed rapid onset of leukemia with a median survival of 37 days." (PMID 37587260, 2023). "Leukemic Cbfb+/56M, Mx1-Cre+, GFP+ mice were intraperitoneally injected with DOXO and leukemia cells from spleen and bone marrow were isolated 48 hours later." (PMID 30742053, 2019). "To test this, we used leukemia cells from Cbfb+/56M, Mx1-Cre+ mice that also express green fluorescent protein (GFP), either from a lentivirus or from a transgene (Cbfb+/56M, Mx1-Cre+, GFP+)." (PMID 30742053, 2019). "Here we show that when we delete PTEN in HSCs using the Mx1–Cre system, p110β ablation prevents MPN, improves HSC function and suppresses leukaemia initiation." (PMID 26442967, 2015). "We performed flow cytometric analysis to characterize the cellular distribution of the R26PR;Mx1-cre and R26PR;MMTV-cre leukemias." (PMID 24046360, 2013). "Notably, these pathways were also enriched in the DEGs identified in the AMP population between Mx1-CreCbfb+/56M and Runx1+/R188QMx1-CreCbfb+/56M mice, further emphasizing their critical role in Cbfb-MYH11–induced leukemia." (PMID 40763310, 2025). "However, once our ETV7Tg mice were crossed with oncogenic Ptenfl/fl;Mx1-Cre mice, ETV7 accelerated PTENΔ/Δ leukemia." (PMID 30478527, 2019).
leukemia (continued). "The fact that the majority of the Mx1-Cre+; Cbfb+/56M; Runx1+/lz mice eventually develop leukemia does not necessarily mean that the fusion protein's RUNX1-independent activities are sufficient for leukemia development, if given enough time." (PMID 27542261, 2016). "YK-4-279 significantly reduced the spleen and liver weights of E/F; Mx1-cre mice with EWS-FLI1 induced leukemia without affecting the total body weight measured at the time of euthanasia." (PMID 26462019, 2015). "Therefore, we performed ChIP for FLAG in unsorted whole bone marrow (BM), which contains a mixture of FLAG-PRDM14 expressing and non-expressing cells, of R26FLPR;Mx1-cre mice 10 days after induction of Prdm14 expression to determine if PRDM14 binds to this region prior to leukemia development." (PMID 27106930, 2016). "Furthermore, co-culture of PKCα-KR cells revealed a significant decrease in the GFP+CD19+ cell number and reduced proliferation of Mx1-Raptor cKO CLL-like cells (and not Mx1-Raptor control cells) upon IFNβ treatment, supporting the role of mTORC1 in promoting leukemia propagation." (PMID 37775560, 2023).
breast carcinoma (30 papers, 2014 to 2025). "Furthermore, mx1 has also been described in human cancer, with the presence of mx1 being linked to metastatic potential in two studies on colorectal and breast cancer." (PMID 38962703, 2024). "Indeed, the increased expression of MX1 is associated with liver fibrosis and high MX1 protein expression is associated with increased proliferation and poor prognosis in breast cancer." (PMID 34361872, 2021). "MX1 has been identified as an independent prognosis indicator in breast cancer and head and neck cancer." (PMID 38201229, 2023). "In this microfluidic chip, a 3D microenvironment is engineered to culture metastatic breast cancer cells (MX1) in a 3D tumor model." (PMID 29642502, 2018). "In breast cancer, expression of an immune response gene subgroup, which includes ISG15, MX1, and other interferon genes, has been associated with improved prognosis in triple negative breast cancers." (PMID 30253781, 2018). "The MX-1 xenograft model was used because it is a well-established model for human breast cancer, one of the indications of the reference product." (PMID 28587612, 2017). "A type I IFN-related transcription signature centered around the expression of MX dynamin-like GTPase 1 (MX1) has been shown to predict the likelihood of 50 breast carcinoma patients to respond to neo-adjuvant anthracycline-based chemotherapy." (PMID 26300886, 2015). "We concluded that correlations between IFNβ1 and MX1 and survival in breast cancer patients exactly reflect relationships identified in vitro, with CAF-induced IFN activity correlating with chemoresistance and consequently poor survival, specifically within claudin-low cancers." (PMID 33398063, 2021). "In contrast, expression of MX1 (a gene signature downstream of type I IFN signaling) is a predictive biomarker for complete response to neoadjuvant anthracycline-based chemotherapy in breast carcinoma." (PMID 34497771, 2021). "Furthermore, MX1 expression also predicted metastasis-free survival with neoadjuvant chemotherapy in breast cancer patients with poor prognosis." (PMID 34497771, 2021). "The expression of MX1 mRNA was assessed at the transcriptomic level using the Molecular Taxonomy of Breast Cancer International Consortium (METABRIC; n = 1980) and validated using three publicly available cohorts on Breast Cancer Gene-Expression Miner (bc-GenExMiner version 4.4)." (PMID 32350677, 2020). "BRCA1 mutant, triple negative HCC1937 and MX1 breast cancer cells were used for the study." (PMID 27220670, 2016). "Thus, through EMT, which is an important mechanism for metastasis of breast carcinoma cells, MX1 may play an essential role in the regulation of tumour progression." (PMID 32350677, 2020). "Conversely, hub genes such as H2BC11, MX1, OAS2, and IFIT3 displayed greater expression in more aggressive breast cancer subtypes." (PMID 41009689, 2025). "STAT3, a typical oncoprotein that promotes chemo-resistant phenotype formation in breast cancers, is activated to a greater extent through tyrosine 705 residue phosphorylation in MCF7/T and MX-1/T cells." (PMID 37242532, 2023). "Of note, in several independent cohorts of breast cancer patients, the ISG MX Dynamin-Like GTPase 1 (MX1) was shown to be upregulated following anthracycline-based therapy and to predict clinical response to treatment." (PMID 34571733, 2021). "However, the top ranked luminal and basal cell lines (luminal: BT483, ZR7530 and 600MPE; basal: HCC70, MX1 and HCC3153) are infrequently used as breast cancer models and account for only 0.4 % of publications on this cell line panel." (PMID 26289960, 2015). "While loss-of-function mutations affecting TLR4 or P2RX7 have a negative impact on the survival of breast cancer patients, local expression of MX1 constitutes a positive prognostic marker." (PMID 26369701, 2015).
melanoma (23 papers, 2015 to 2025). A malignant, usually aggressive tumor composed of atypical, neoplastic melanocytes. "Strikingly, vaccination of MX1-NHAcGD3 elicited high anti-NHAcGD3 IgG antibodies, which effectively recognized human malignant melanoma SK-MEL-28 cells and had a significant CDC effect against this cell line." (PMID 38375005, 2024). "The transient expression of murine GFP-Mx1 in human Huh7 hepatoma, human Mich-2H6 melanoma, and murine NIH 3T3 cells led to the appearance of Mx1 nuclear bodies." (PMID 33077519, 2020). "MX Dynamic Like GTPase 1, or Myxovirus resistance 1 (MX1), is a protein-coding gene that resulted upregulated in other solid tumors as infiltrating breast cancer, melanoma, prostatic adenocarcinoma, and even an independent poor prognostic factor in head and neck squamous cell carcinoma." (PMID 36831458, 2023). "R.E treatment enhanced pathwaysassociated with immune activation, including upregulation of ISGssuch as IRF1, MX1, and CXCL1, as well as pro-inflammatory cytokinesincluding TNF and IL6 in melanoma cells." (PMID 41341044, 2025). "Cytokine profiling of SPOP-depleted human melanoma A2058 cells revealed increased expression of interferon-stimulated genes (ISGs), including IFIT1, CXCL10, and MX1, which was validated by RT-PCR." (PMID 41148213, 2025). "We used mRNA expression of the type I IFN-responsive genes Ly6E, MX1, IFI44L and IFITM1 to determine the pre-treatment type I IFN score in the PBMCs from the melanoma patients in our study." (PMID 38967829, 2024). "The conjugate of MX1 to NHAcGD3 induces potent NHAcGD3-specific IgG antibodies, which bound firmly to SK-MEL-28 melanoma cells and mediated significant CDC killing." (PMID 38375005, 2024). "Not much information is available concerning MX1 and MX2 during SARS-CoV-2 infection; however, in melanoma cell lines, it was reported that persistent IFN-γ stimulation increases the expression and genome occupancy of STAT1 and induces the expression of ISGs, such as IFIT1 and MX1." (PMID 36298734, 2022). "However, we also identified three interferon-stimulated genes (ISGs)—IFI6, IFI27, and MX1—that have not been previously implicated in oncogenic NRAS-induced transformation and melanoma tumor growth." (PMID 27608486, 2016).
ZIKV infection (22 papers, 2017 to 2025). "To better elucidate the dynamics between ZIKV infection and the antiviral state in SC, we next sought to evaluate ZIKV infection kinetics and its association with MX1 protein levels in SC over time." (PMID 34079533, 2021). "We found that increased levels of MX1 at the later time points of infection coincided with diminished ZIKV infection while the silencing of MX1 and IFIT1 enhanced peak ZIKV propagation in SC." (PMID 34079533, 2021). "The data in this study highlight IFN-I as a driver of the antiviral state that limits ZIKV infection in SC and suggests that MX1 and IFIT1 function as antiviral effectors against ZIKV in SC." (PMID 34079533, 2021). "Collectively, these data indicate that proteins involved in innate antiviral defense are the most prominent dysregulated proteins in SC during peak ZIKV infection, with MX1 and IFIT1 as the top upregulated proteins detected." (PMID 34079533, 2021). "LC-MS/MS analysis identified MX1 as the top upregulated antiviral protein in SC during peak ZIKV infection." (PMID 34079533, 2021). "Our study also found that in CHME3 cells ZIKV infection resulted in upregulation of type I interferon (IFNβ), interferon-stimulated genes (MX-1 and ISG15), pattern recognition receptors (RIG-I and MDA5) and IRF7." (PMID 32373079, 2020). "During ZIKV infection in this individual, there was similar strong induction of type I ISGs, exemplified by MX1, OAS3, RSAD2, and IFI27 genes (Cluster 2), but minimal coincident induction of chemokines involved in leukocyte chemotaxis (Cluster 1)." (PMID 30596671, 2018). "RNA-seq analysis of HT-29 cells revealed that ZIKV infection caused the upregulation of IFNB and several innate immune response genes, including FAM60A, IFI6, DDX58, OAS1, MX1, and IP-10." (PMID 30333476, 2018). "MX1 was reported to be changed as an antiviral gene and immune response factor in patients with hypogammaglobulinemia, lupus nephritis, Zika virus infection, lupus erythematosus and so on." (PMID 38406276, 2024). "The dynamic between IFN response and ZIKV infection kinetics in SC remains unclear, therefore we further determined whether MX1 and IFIT1 serve as antiviral effectors against ZIKV." (PMID 34079533, 2021). "Furthermore, both IFN-β treatment and ZIKV infection induced the expression of MX1 and IFIT1." (PMID 34079533, 2021). "During ZIKV infection, MEL reduces expression of TNFα, MX1 and IFI44L but significantly increases expression of IL-1β and IFNβ." (PMID 40821819, 2025). "Generation of innate AVPs, including OAS1, OAS2, OASL, and MX1, in response to IL27 was found to be protective against Zika virus infection in human keratinocytes." (PMID 37310504, 2023). "Our data demonstrated that interferon (IFN) signaling was the most significantly enriched pathway and the antiviral proteins MX1 and IFIT1 were among the top upregulated proteins in SC following ZIKV infection." (PMID 34079533, 2021). "Upon ZIKV infection, IFN-λ and the ISGs IFIT1 and Mx1 were selectively induced in the reconstituted cells, thus excluding off-target effects of the RIG-I KO." (PMID 33658344, 2021). "Our data collectively suggest that MX1 and IFIT1 are potent markers of the antiviral state in SC in response to ZIKV infection." (PMID 34079533, 2021). "While MX1 and IFIT1 were the top upregulated proteins in SC following ZIKV infection, a major highlight of this study was that these proteins were also shown to restrict ZIKV replication in SC." (PMID 34079533, 2021). "During ZIKV infection, MEL reduced TNFα, MX1, and IFI44L levels." (PMID 40821819, 2025). "Mice on the C57BL/6 background carry nonfunctional alleles of the Mx1 gene, and Mx1 is not a relevant ISG that restricts ZIKV infection." (PMID 34379510, 2021).
ZIKV infection (continued). "These included MX1, IFIT1, ISG15, SAMHD1, IFIT3, and STAT1, all of which have been shown to be similarly upregulated by ZIKV infection in other human cell types, including fibroblasts and pluripotent stem cell (iPSC)-derived neural progenitor cells (NPC), as also demonstrated by LC-MS/MS analysis." (PMID 34079533, 2021).